SPINK13 (serine peptidase inhibitor Kazal type 13)
Description:
May be a serine protease inhibitor (By similarity). Essential for sperm maturation and fertility. Inhibits sperm acrosome reaction, protecting sperm from premature reaction (By similarity).
Synonyms: HBVDNAPTP1; SPINK5L3; LiESP6; HESPINTOR; MGC149260
Tractability: Antibody: UniProt places it where antibodies can reach, with medium confidence; UniProt predicts a signal peptide or a membrane-spanning region; its Gene Ontology location is reachable by antibodies, with medium confidence; the Human Protein Atlas places it where antibodies can reach. PROTAC: ubiquitination databases record sites on it.
Gene: Protein-coding gene on chromosome 5 (148,268,180 to 148,286,255, forward strand). Ensembl gene ENSG00000214510.
Subcellular location: Secreted
Subcellular location (Human Protein Atlas): Plasma membrane; Nucleoplasm; Predicted to be secreted
Gene Ontology:
Molecular function: protein binding
Biological process: negative regulation of acrosome reaction
Cellular component: extracellular region
Genetic constraint (gnomAD): Loss-of-function variants: 8 observed, 6.75 expected, observed/expected ratio (o/e) 1.19, 90% interval 0.68 to 1.85. That is too few expected variants to judge how well the gene tolerates losing a copy. Missense variants: 82 observed, 83.92 expected, observed/expected ratio (o/e) 0.98, 90% interval 0.82 to 1.17. Synonymous variants: 26 observed, 27.91 expected, observed/expected ratio (o/e) 0.93, 90% interval 0.68 to 1.29.
Homologues: Orthologues: chimpanzee SPINK13 (98% identical), macaque SPINK13 (73% identical), rabbit SPINK13 (67% identical), mouse Spink13 (52% identical), rat Spink13 (52% identical). Paralogues in human: SPINK14 (31% identical), SPINK2 (28% identical), SPINK9 (26% identical), SPINK7 (23% identical), SPINK8 (18% identical).
Diseases named in the same sentence as SPINK13 in open-access papers:
SPINK13 is named in the same sentence as 7 diseases in open-access papers, as found by Europe PMC text mining. Sharing a sentence is not in itself a finding about the gene and the disease. The quoted sentences say what the papers report.
hepatocellular carcinoma (2 papers, 2022 to 2025). A malignant tumor that arises from hepatocytes. "SPINK13 has been identified as a tumor suppressor in hepatocellular carcinoma (HCC), where it inhibits Akt phosphorylation, a key regulator of cancer cell survival, and proliferation." (PMID 40872585, 2025).
ovarian carcinoma (2 papers, 2022 to 2025). A malignant neoplasm originating from the surface ovarian epithelium. "In ovarian cancer, SPINK13 overexpression is associated with improved survival rates, while immunohistochemical analyses show significantly lower protein levels in cancerous tissues compared to normal ones." (PMID 40872585, 2025). "This suggests SPINK13 may serve as a tumor suppressor and potential biomarker for ovarian cancer diagnosis and prognosis." (PMID 40872585, 2025).
lung adenocarcinoma (1 paper, 2022). A carcinoma that arises from the lung and is characterized by the presence of malignant glandular epithelial cells. "CAPN8, IRX2, and SPINK13 may serve as novel targets of targeted and immune‐based therapies in lung adenocarcinoma." (PMID 35102706, 2022). "Our results signaled that IRX2, SPINK13, and CAPN8 could serve as novel therapeutic targets to prevent tumor growth in lung adenocarcinoma." (PMID 35102706, 2022). "The present study uncovered that high expression of IRX2, SPINK13, and CAPN8 could facilitate tumor progression in LUAD with multiple lung adenocarcinoma cell lines." (PMID 35102706, 2022).
male infertility (1 paper, 2018). The inability of the male to effect fertilization of an ovum after a specified period of unprotected intercourse. "Previous studies suggested that disruptions of CAMK4 located on chromosome 5q22.1, SPINK13 located on chromosome5q32 and the testis-specific serine/threonine kinase (TSSK1B) gene mapped to chromosome 5q22.2 were associated with loss of sperm function and human male infertility." (PMID 29416565, 2018).
tumor (5 papers, 2020 to 2025). "In contrast, SPINK13 serves as a tumor suppressor in HCC, blocking Akt phosphorylation and lowering cancer cell growth and survival." (PMID 40872585, 2025). "SPINK13 has been recognised as a tumor suppressor in HCC, mainly by suppressing Akt phosphorylation." (PMID 40872585, 2025). "In a nude mouse xenograft tumor model of HCC, endogenous SPINK13 had a significant tumor-suppressive effect, and its mechanism of action was consistent with the results of in vitro experiments." (PMID 39537605, 2024). "Due to its tumor-suppressive properties and influence on key oncogenic pathways, further research on SPINK13’s interactions with uPA and downstream signalling mechanisms could provide valuable insights into its therapeutic potential in cancer treatment." (PMID 40872585, 2025). "On the other hand, SPINK13 was the best, whether in terms of discerning tumor cells, its correlation with advanced tumors, or promoting proliferation in vitro." (PMID 35102706, 2022). "Collectively, the expression status of IRX2, SPINK13, and CAPN8 was in line with our findings in scRNA‐seq that they all showed an elevation both in tumor tissues and cells, which was also coincided with the development of tumor stage in LUAD." (PMID 35102706, 2022). "Three genes in the model, IRX2, SPINK13, and CAPN8, were also validated with their expression and potentials in tumor proliferation." (PMID 35102706, 2022). "SPINK13 induces mitochondrial apoptosis and cell cycle arrest by triggering the Notch1/Hes1-PTEN/Akt signaling axis and reversing EMT, thereby inhibiting HCC cell nude mouse xenograft tumor subcutaneous growth." (PMID 39537605, 2024). "Moreover, we found that IRX2, SPINK13, and CAPN8 showed great superiority to their counterparts in differentiation, especially in the ability to distinguish malignant tumor cells from normal epithelial cells." (PMID 35102706, 2022). "Our results signaled that IRX2, SPINK13, and CAPN8 could serve as novel therapeutic targets to prevent tumor growth in LUAD." (PMID 35102706, 2022). "However, neither of its expression in single tumor cells or LUAD tissues was satisfied, which we considered was attributed to its feature that SPINK13 was a secreted protein." (PMID 35102706, 2022).
cancer (2 papers, 2024 to 2025). A tumor composed of atypical neoplastic, often pleomorphic cells that invade other tissues. "Beyond reproductive functions, SPINK13 has been implicated in cancer, particularly ovarian and RCC." (PMID 40872585, 2025). "In vitro studies demonstrate that SPINK13 inhibits cell proliferation, enhances apoptosis, and suppresses migration and EMT by downregulating uPA, a key enzyme in cancer progression." (PMID 40872585, 2025).
SPINK13 also shares sentences with these, for which no sentence is quoted: renal cell carcinoma (1 paper).